INSIG1 (insulin induced gene 1)
Description:
Oxysterol-binding protein that mediates feedback control of cholesterol synthesis by controlling both endoplasmic reticulum to Golgi transport of SCAP and degradation of HMGCR. Acts as a negative regulator of cholesterol biosynthesis by mediating the retention of the SCAP-SREBP complex in the endoplasmic reticulum, thereby blocking the processing of sterol regulatory element-binding proteins (SREBPs) SREBF1/SREBP1 and SREBF2/SREBP2. Binds oxysterol, including 25-hydroxycholesterol, regulating interaction with SCAP and retention of the SCAP-SREBP complex in the endoplasmic reticulum. In presence of oxysterol, interacts with SCAP, retaining the SCAP-SREBP complex in the endoplasmic reticulum, thereby preventing SCAP from escorting SREBF1/SREBP1 and SREBF2/SREBP2 to the Golgi. Sterol deprivation or phosphorylation by PCK1 reduce oxysterol-binding, disrupting the interaction between INSIG1 and SCAP, thereby promoting Golgi transport of the SCAP-SREBP complex, followed by processing and nuclear translocation of SREBF1/SREBP1 and SREBF2/SREBP2. Also regulates cholesterol synthesis by regulating degradation of HMGCR: initiates the sterol-mediated ubiquitin-mediated endoplasmic reticulum-associated degradation (ERAD) of HMGCR via recruitment of the reductase to the ubiquitin ligases AMFR/gp78 and/or RNF139. Also regulates degradation of SOAT2/ACAT2 when the lipid levels are low: initiates the ubiquitin-mediated degradation of SOAT2/ACAT2 via recruitment of the ubiquitin ligases AMFR/gp78.
Synonyms: CL-6; MGC1405; CL6
Tractability: Antibody: UniProt predicts a signal peptide or a membrane-spanning region. PROTAC: UniProt records ubiquitination sites on it; ubiquitination databases record sites on it.
Gene: Protein-coding gene on chromosome 7 (155,296,731 to 155,311,963, forward strand). Ensembl gene ENSG00000186480.
Subcellular location: Endoplasmic reticulum membrane
Subcellular location (Human Protein Atlas): Vesicles
Pathways (Reactome):
Metabolism: Regulation of cholesterol biosynthesis by SREBP (SREBF)
Gene Ontology:
Molecular function: oxysterol binding; protein binding; protein sequestering activity
Biological process: cellular response to sterol; cholesterol biosynthetic process; cholesterol homeostasis; negative regulation of cargo loading into COPII-coated vesicle; negative regulation of cholesterol biosynthetic process; SREBP signaling pathway; SREBP-SCAP complex retention in endoplasmic reticulum; cellular response to insulin stimulus; cholesterol metabolic process; regulation of transcription by RNA polymerase II
Cellular component: endoplasmic reticulum; endoplasmic reticulum membrane; SREBP-SCAP-Insig complex
Genetic constraint (gnomAD): Loss-of-function variants: 12 observed, 19.1 expected, observed/expected ratio (o/e) 0.63, 90% interval 0.4 to 1.02. The upper end of that interval is the gene's LOEUF score, 1.02, which puts it in group 4 of 6, group 1 being the genes least tolerant of losing a copy. Missense variants: 256 observed, 314.38 expected, observed/expected ratio (o/e) 0.81, 90% interval 0.73 to 0.9. Synonymous variants: 137 observed, 137.53 expected, observed/expected ratio (o/e) 1, 90% interval 0.87 to 1.15.
Homologues: Orthologues: chimpanzee INSIG1 (99% identical), macaque INSIG1 (97% identical), rabbit INSIG1 (85% identical), pig INSIG1 (85% identical), dog INSIG1 (81% identical), rat Insig1 (80% identical), mouse Insig1 (79% identical), guinea pig INSIG1 (78% identical), rat LOC120102490 (76% identical), tropical clawed frog insig1 (73% identical), zebrafish insig1 (68% identical). Paralogues in human: INSIG2 (59% identical).
Diseases named in the same sentence as INSIG1 in open-access papers:
INSIG1 is named in the same sentence as 61 diseases in open-access papers, as found by Europe PMC text mining. Sharing a sentence is not in itself a finding about the gene and the disease. The quoted sentences say what the papers report.
Obesity (10 papers, 2014 to 2025). Accumulation of substantial excess body fat. "In the present study, we investigated associations between three SNPs in the INSIG1 gene and obesity risk in a Chinese Uygur population." (PMID 31658356, 2019). "In the present study, we investigated the interaction of INSIG1 polymorphisms in obesity through linkage disequilibrium analysis and the results showed the strong linkage disequilibrium among INSIG1 rs2721, rs9767875 and rs9719268 polymorphisms." (PMID 31658356, 2019). "This study revealed that rs2721 and rs9719268 of INSIG1 gene are associated with obesity in Uygur subjects." (PMID 31658356, 2019). "The INSIG1 rs2721/ rs9767875/ rs9719268 haplotype G-G-T and T-G-G were significantly associated with increased risk of obesity (OR = 1.984, 95% CI = 1.186-3.320, P = 0.008; OR = 1.512, 95% CI = 1.170–1.953, P = 0.001)." (PMID 31658356, 2019). "In the present study, we genotyped polymorphisms of rs2721, rs9767875 and rs9719268 in INSIG1 gene and found that rs2721 and rs9719268 were associated with obesity." (PMID 31658356, 2019). "Additional studies need to be undertaken to clarify the underlying molecular mechanism between INSIG1 gene polymorphisms and obesity." (PMID 31658356, 2019). "In humans, INSIG1 variants have been shown to influence obesity-related hypertriglyceridemia." (PMID 35945490, 2022). "In the present study, our primary objective was to explore whether the single nucleotide polymorphisms (SNPs) in INSIG1 gene were associated with obesity in Uygur subjects, in Xinjiang, China." (PMID 31658356, 2019). "The association between INSIG1 gene polymorphisms and obesity was poor." (PMID 31658356, 2019). "Expression of INSIG1 increased in fat tissue of normal mice constitutively with diet-induced obesity." (PMID 31910243, 2020). "Studies have indicated that INSIG-1 increases in the fat tissue of mice developing diet induced obesity and also in differentiating 3 T3-L1 preadipocytes." (PMID 29690861, 2018). "We next posited that the less harmful composition of the hepatic lipidome in the Insig1 KO mice, leading to reduced hepatocellular damage in the obesity-specific WDSW challenge, might also be protective in the context of other forms of liver damage." (PMID 33722690, 2021). "Furthermore, the gp78 knockout mice were resistant to normal chow diet-induced and western-type diet-induced obesity due to the suppression of SREBP via upregulation of its negative regulators, Insig1/219." (PMID 35637957, 2022). "In addition, increased expression of Insig1 in the liver and in WAT may reduce cholesterol biosynthesis, resulting in obesity and dyslipidemia." (PMID 30453990, 2018).
breast carcinoma (7 papers, 2010 to 2025). "HFD significantly down-regulated many of the genes found to be up-regulated in a lipid metabolic gene network associated with human breast cancer (e.g. Acyl, Insig1, Elovl6, Fasn, Scd)." (PMID 20435547, 2010). "Other upregulated genes are related to poor prognoses in breast cancer, such as acetyl-CoA carboxylase (ACC), insulin-induced gene 1 (INSIG1), and sterol regulatory element-binding protein 1 (SREBP1)." (PMID 34940418, 2021). "In MCF-7 breast cancer cells, SRA silencing decreased mRNA levels of insulin-induced gene 1 protein (INSIG1) and cholesterol transporter ATP-binding cassette transporter ABCA1, suggesting its role in lipids/cholesterol homeostasis." (PMID 33123488, 2020). "One of these genes is insulin-induced gene 1 protein (INSIG1), which is regulated by insulin and plays a role in blocking cholesterol biosynthesis by interacting with the SCAP-SREBP complex was found to be correlated with breast cancer cell viability." (PMID 38812058, 2024).
Hepatic steatosis (7 papers, 2015 to 2024). Steatosis is a term used to denote lipid accumulation within hepatocytes. "Insulin induced gene 1 protein (Insig 1), a gene that has been associated with hepatic steatosis in zebrafish, showed one of the largest fold changes among the DE genes in the 36 dph larvae." (PMID 31729401, 2019). "Further evidence for a coordinate responses in fatty liver disease was obtained by considering regulation of the ER lipid raft associated 2, PPARγ and insulin induced gene 1 by miR-192-5p." (PMID 27045805, 2016). "The findings from this study suggest that miR29c may provide geese tolerance against severe hepatic steatosis by modulating energy homeostasis and tissue growth and that its function is mediated by its target genes, Col3a1, Sgk1, and Insig1." (PMID 30400792, 2018). "The results suggested that Col3a1, Sgk1 and Insig1 were most likely to be the target genes of miR29c in the development of goose fatty liver, which was supported by the complete match of the 3’ UTR sequences of the genes to the core sequence of goose mature miR29c (note: Col3a1 had two matches)." (PMID 30400792, 2018). "Based on the functions of Col3a1, Sgk1 and Insig1 in cell growth, we conclude that miR29c may participate in tissue growth during the development of goose fatty liver, which enables the goose liver to tolerate severe steatosis at the end of the overfeeding period." (PMID 30400792, 2018). "Among that, PCK1-mediated phosphorylation of INSIG1/2 could promote the activation of SREBP1 lipogenesis, and AQP9 could facilitate the hepatic uptake of glycerol and knockdown of the AQP9, thereby reducing hepatic steatosis." (PMID 38665091, 2024).
atherosclerosis (5 papers, 2018 to 2024). A disease characterized by the build-up of fatty material and calcium deposition in the arterial wall resulting in partial or complete occlusion of the arterial lumen. "Nr1d2 also represses the expression of hepatic Apoc3 mRNA, a risk factor for atherosclerosis, and hepatic Insig1 overexpression reduces lipogenesis via decreased expression of Srebp1c mRNA and its target enzymes." (PMID 30423963, 2018). "miR-24 has also been shown to aggravate atherosclerosis by inhibiting genes involved in lipogenesis (e.g., insulin-induced gene 1 (INSIG1), an inhibitor of lipogenesis) and HDL uptake (SR-BI)." (PMID 31847094, 2019). "In this context, the high expression of miR-24 was demonstrated in HFD mice livers, human hepatocytes incubated with fatty acids, and by directly repressing insulin-induced gene 1 (Insig1), an inhibitor of lipogeneses, which can lead to lipid accumulation and atherosclerosis." (PMID 37371692, 2023). "In addition, GSTA4, RAPGEF3, TRPV4, INSIG1, UTS2, and PPP1R1A all play a role in the development of atherosclerosis." (PMID 39758846, 2024).
dyslipidemia (5 papers, 2014 to 2024). "The results in the present study indicated that the mutation of INSIG1 rs9769826 may aggravate the dyslipidemia, especially for increased CHOL in male patients with schizophrenia than female." (PMID 38760414, 2024). "In this study, three CpG sites in MBTPS1, two CpG sites in INSIG1, one CpG site in INSIG2, seven CpG sites in FBXW7, and six CpG sites in AMFR were found to be associated with dyslipidemia." (PMID 36570009, 2022). "The deep mechanistic roots of the ASGR/INSIG1 linkage are worth clarifying and uncover potential targets for cholesterol-lowing drug and dyslipidemia treatment development." (PMID 34622799, 2021). "Furthermore, this study was the first to discover that several CpG sites in genes involved in lipid metabolism (AMFR, FBXW7, INSIG1/2, MBTPS2) are associated with dyslipidemia." (PMID 36570009, 2022). "Recently, interaction of INSIG1 and INSIG2 on antipsychotic induced metabolic syndrome was also reported." (PMID 25028659, 2014).
Insulin resistance (5 papers, 2015 to 2024). Increased resistance towards insulin, that is, diminished effectiveness of insulin in reducing blood glucose levels. "INSIG1 mRNA down-regulation has been observed in adipose tissue from obese mice and humans, and may function to ameliorate adipocyte insulin resistance." (PMID 26678390, 2015). "In this scenario, a decrease in INSIG1 expression leads to an increase in SREBP1 maturation, increased lipogenesis and facilitation of fat storage despite insulin resistance." (PMID 39152223, 2024).
gastric cancer (4 papers, 2019 to 2025). A primary or metastatic malignant neoplasm involving the stomach. "Promoter methylation of INSIG-1 has been shown in gastric cancer." (PMID 39728572, 2024). "Loss of genes, such as INSIG1 and ACSS2, is responsible for the advancement of gastric cancer, but inactivation of these genes may be linked with the development of BRCA." (PMID 31311202, 2019).
hepatocellular carcinoma (4 papers, 2021 to 2025). A malignant tumor that arises from hepatocytes. "Knockout of INSIG1 or INSIG2 in human hepatoma Huh7 cells attenuated ATF4 protein upregulation, indicating that only one of the endogenous INSIGs, unlike overexpression of intrinsic INSIG1 or INSIG2, was insufficient for ATF4 induction." (PMID 34298014, 2021).
steatosis (4 papers, 2018 to 2025). Increased lipid within the cytoplasm of cells. "Using our imaging data to identify in vivo drivers of steatosis, we observed that knockout of Insig1, the growth inhibitor Pten86, the ISR inhibitor Eif2α (Eif2s1), and the alanine-tRNA synthetase Aars all caused steatosis, as measured by enlargement and signal increase of lipid droplets." (PMID 40513557, 2025).
colon cancer (2 papers, 2022 to 2025). "Furthermore, peptide treatment inhibited Insig1 S207 phosphorylation and induced cell death in HCT116 human colon cancer cells." (PMID 40959854, 2025). "An upregulation trend of INSIG1 was also seen in cediranib-resistant NSCLC, BV-resistant colon cancer, and BV non-responding CRC." (PMID 36110213, 2022).
diabetes (2 papers, 2020 to 2025). "Among them, 89 upregulated and 24 downregulated DEGs were found to be associated with diabetes progression (e.g., Ctrb1, Cpa2, and Insig1) and diabetes (e.g., Car3, Dio1, and Mup5), respectively." (PMID 33329383, 2020).
fibrosis (2 papers, 2018 to 2021). the formation of excess fibrous connective tissue in an organ or tissue in a reparative or reactive process. "Livers of patients with fibrosis (all F1 apart from 1 patient whom was F2) had up-regulations of PPARG (20%), INSIG1 (39%), SRB1 (11%), NPC1 (13%), and NPC2 (30%) (all P < 0.05)." (PMID 29522534, 2018).
glioma (2 papers, 2017 to 2022). A benign or malignant brain and spinal cord tumor that arises from glial cells (astrocytes, oligodendrocytes, ependymal cells). "In this study, we screen three expression arrays associated with the BV resistance of glioma, OV, and NSCLC from the GEO database and identified two DEGs including INSIG1 and AKAP12, both upregulated in the BV-resistant cancer group." (PMID 36110213, 2022). "Genes involved in the regulation of the mevalonate pathway (INSIG1 and SREBF2 but not SREBF1) were also downregulated in dense NHAs but not glioma cells." (PMID 28118603, 2017).
Hypercholesterolemia (2 papers, 2014 to 2020). An increased concentration of cholesterol in the blood. "Moreover, 5-uRCK and ellagic acid treatment significantly increased the expression of AMPK, p-AMPK, p-HMGCR, and INSIG-1 and decreased the expression of HMGCR and mSREBP-2 in a HCD-induced hypercholesterolemia rat model." (PMID 33339214, 2020).
hyperlipidemia (2 papers, 2018 to 2023). "Together, these findings suggest that suppression of miR29c in energy homeostasis related tissues, as a response to hyperglycemia and hyperlipidemia, may play a part in goose fatty liver by modulating energy metabolism via its target genes, Insig1, Sgk1 and Col3a1." (PMID 30400792, 2018).
lung carcinoma (2 papers, 2011 to 2025). "In the lung cancer cell line H1299, TET1 is required for the expression of mesenchymal genes N-cadherin and vimentin as well as for the expression of INSIG1, a master regulator of cholesterol biosynthesis that drives hypoxia-induced EMT in a catalytic-site independent manner." (PMID 40764968, 2025).
melanoma (2 papers, 2017 to 2022). A malignant, usually aggressive tumor composed of atypical, neoplastic melanocytes. "Although HERPUD1, INSIG1 and MMS22L were mutated in more than one of the melanoma cell lines, only Ma-Mel-86a cells were recognized by the respective T cell clones." (PMID 28423700, 2017). "To address this question, we generated MEL624 melanoma PGCC and assessed changes in HMGCR and INSIG1 after LCL521 treatment." (PMID 35624221, 2022).
prostate carcinoma (2 papers, 2018 to 2022). A carcinoma that arises from epithelial cells of the prostate gland. "As in PPC1 prostate cancer cells, we detected a highly significant increase in INSIG1 mRNA and a smaller, but also significant increase in HMGCR following ASAH1 inhibition in PGCC." (PMID 35624221, 2022). "This suggests that some HMGCR activity can be maintained through downregulation of INSIG1, and that targeting HMGCR degradation can be an interesting option for modulating cholesterol levels in prostate cancer." (PMID 29703166, 2018).
agranulocytosis (1 paper, 2021). "The lead variant and its LD proxies at the INSIG1 locus are located in an intergenic region close to another gene HTR5A (5-hydroxytryptamine receptor 5A), which has been reported for sulfasalazine-induced agranulocytosis in EA populations." (PMID 34107879, 2021).
cholestasis (1 paper, 2024). Impairment of the bile flow caused by obstruction within the liver, or outside the liver in the bile duct system. "CSA, a well-known inducer of cholestasis, downregulated gene expression of CYP7A1, CYP27A1, BAAT, HNF4A, and INSIG1, while it upregulated ACAT2 and CCL20 gene expression." (PMID 38953992, 2024).
chronic kidney disease (1 paper, 2024). Impairment of the renal function secondary to chronic kidney damage persisting for three or more months. "Chronic kidney disease (CKD) mice with loss of Insulin-induced gene 1 (Insig1) in proximal tubule cells (PTCs) exhibit increased NAD+ consumption and worsened renal fibrosis, indicating that activation of Insig1 may offer a new approach to treating CKD." (PMID 38806641, 2024). "Together, our findings support tubular Insig1 as a new therapeutic target for chronic kidney disease (CKD)." (PMID 38806641, 2024).
colorectal adenocarcinoma (1 paper, 2019). The most common type of colorectal carcinoma. "Additionally, a recent study reports upregulation of INSIG-1 (insulin-induced gene 1) and alteration in intracellular cholesterol trafficking in Caco2 colorectal adenocarcinoma cells." (PMID 31060335, 2019).
coronary heart disease (1 paper, 2022). "INSIG1 gene single nucleotide polymorphisms were associated with coronary heart disease risk in the Chinese Han population." (PMID 35795669, 2022).
diabetic kidney disease (1 paper, 2024). Progressive kidney disorder caused by vascular damage to the glomerular capillaries, in patients with diabetes mellitus. "Recent evidence indicates that Insig1 expression is downregulated in kidney diseases such diabetic kidney disease (DKD) and renal mass loss, but no study has been done to determine the effect of Insig1 deficiency in the pathophysiology of CKD or PTCs fibrosis." (PMID 38806641, 2024).